CTBP1-DT (CTBP1 divergent transcript)
Description:
Promotes DNA damage repair through both homologous recombination repair (HRR) and post-replication repair (PRR) mechanisms. Enhances the retention of DNA damage response protein RAD18 at sites of DNA damage. This allows for HRR via association of RAD18 with RAD51C and for PRR via RAD18-mediated promotion of PCNA monoubiquitination.
Synonyms: DDUP; MGC21675; C4orf42; CTBP1-AS1; CTBP1-AS2
Gene: Long non-coding RNA gene on chromosome 4 (1,248,877 to 1,288,856, forward strand). Ensembl gene ENSG00000196810.
Subcellular location: Nucleus; Chromosome